RBM15 (RNA binding motif protein 15)
Diseases named in the same sentence as RBM15 in open-access papers (continued):
Sharing a sentence is not in itself a finding about the gene and the disease.
tumor (continued). "Given that RBM15 depletion reduces fumarate levels, which could potentially enhance CD8+ T cell activation and increase anti-tumor immune responses, we next determine whether RBM15 deficiency could inhibit tumorigenesis via enhanced immune surveillance." (PMID 40370450, 2025). "In addition, we examined the influence of RBM15/TNFSF9 on the polarization state of macrophages within the TNBC tumor microenvironment, further elucidating the molecular mechanisms of PTX resistance in TNBC." (PMID 40830812, 2025). "CCK‐8 assay showed that RBM15 knockdown negatively impacted the tumor cell growth." (PMID 41038802, 2025). "We noticed that silencing of Rbm15 may inhibit tumor cell viability and suppress tumor growth in the xenograft mouse model." (PMID 40666518, 2025). "Of particular note, the role of RBM15 in tumor immunity has recently attracted growing attention." (PMID 41403702, 2025). "A tumor xenograft assay was conducted to verify the role of RBM15 in LC." (PMID 39039611, 2024). "Furthermore, our experiments demonstrated that RBM15 downregulation significantly inhibited lung and liver metastasis of tumor cells, while KLF1 overexpression and TRIM13 downregulation significantly promoted lung and liver metastasis (p < 0.05)." (PMID 39716068, 2024). "We also found the dependence of STARD14 on RNA methylation levels in LUAD, including the correlation with HNRNPA2B1, IGF2BP2, RBM15 and RBM15, which could participate in the tumor progression of LUAD." (PMID 37790851, 2023). "Previous reports suggest that RBM15 plays a significant role in tumor development." (PMID 37474926, 2023). "Then we verified the of RBM15 in CC growth by establishing mouse xenograft tumor models." (PMID 37474926, 2023). "Tumor xenograft models were used to assess the effects of RBM15 on tumorigenesis." (PMID 37474926, 2023). "In terms of methylation, the expression level of ECE2 was significantly negatively correlated with HNRNPC, IGF2BP1, IGF2BP3 and RBM15, which may affect the tumor progression of LUAD by affecting the m6A methylation level." (PMID 36299451, 2022). "Furthermore, the correlation between RBM15 and immune checkpoint markers implies an important role of RBM15 in regulating tumor immunity, especially in PAAD." (PMID 35223996, 2022). "In contrast, the expression of RBM15 was obviously reduced in the tumor area." (PMID 35559019, 2022). "Based on univariate Cox and LASSO regression, a risk model consisting of three high-risk genes (KIAA1429, RBM15, FTO) was established, and the expression difference between normal and tumor tissues of three genes was confirmed by immunohistochemical results of our clinical tissues." (PMID 36389678, 2022). "While YTHDF2, RBM15, ZC3H13, METTL3, HNRNPC, YTHDC1 with m6a modifications had higher expression in the low risk group, indicating that they might be tumor suppressors." (PMID 36199800, 2022). "RNA binding motif protein 15 (RBM15), whose function is to bind the m6A complex and recruit it to a unique RNA site, also takes part in numerous regulations, including the proliferation and migration of tumor cells, and macrophage infiltration." (PMID 36468034, 2022). "However, as expected, when AMC-HN-8 cells with down-regulated RBM15 expression were injected, the xenograft tumour volume was significantly reduced compared to the control group." (PMID 33637103, 2021). "In addition, differential expression analysis of GSE12865 through a permutation test further confirmed that the expression of RBM15 was significantly upregulated in the tumor tissues." (PMID 32582536, 2020). "Finally, we verified that RBM15 promoted tumor growth by mediating SRSF1 in vivo." (PMID 40923717, 2026). "Little is known about whether or how RBM15 regulates tumor immune surveillance in cancers." (PMID 40370450, 2025). "However, whether RBM15 plays a role in metabolic reprogramming that could affect anti-tumor immunomodulation remains poorly understood." (PMID 40370450, 2025).
tumor (continued). "Importantly, RBM15 deletion suppresses tumor growth in vivo." (PMID 41403702, 2025). "From the Sankey diagram, it was clear that RBM15, YTHDC1, and YTHDC2 were associated with more lncRNAs ― over 37% (147/397) ― indicating that these methylation-related enzymes have important catalytic and recognition roles in the occurrence of the tumor formation induced by ALV-J infection." (PMID 35529873, 2022). "Furthermore, natural compounds may modulate RBM15-mediated tumor regulation." (PMID 41403702, 2025). "RBM15, as an m6A RNA methyltransferase, is upregulated in ESCC and promotes tumor proliferation and migration." (PMID 41403702, 2025). "In xenograft models, silencing RBM15, IGF2BP3, or YTHDF2 significantly reduces VEGFA expression and suppresses tumor growth." (PMID 41403702, 2025). "Mechanistic studies demonstrate that RBM15 stabilizes CXCL11 mRNA in an m6A-dependent manner, thereby enhancing macrophage infiltration and M2 polarization, which collectively promote tumor progression." (PMID 41403702, 2025). "Mechanistically, RBM15 promotes CC progression by installing m6A modification on the tumor suppressor DCN mRNA, thereby reducing DCN expression; conversely, RBM15 silencing enhances DCN expression, while DCN depletion reverses this tumor-suppressive effect." (PMID 41403702, 2025). "Clinical analyses further reveal a positive correlation between VEGFA expression and RBM15/IGF2BP3/YTHDF2 levels, underscoring the central role of RBM15-mediated m6A modification in VEGFA regulation and tumor angiogenesis." (PMID 41403702, 2025). "What’s more, through WB analysis of tumor tissues, we further verified the existence of a clear positive correlation between TNFSF9 and RBM15 in tumors." (PMID 40830812, 2025). "In summary, this study has unveiled an important finding: RBM15 may exacerbate the resistance of TNBC to PTX and accelerate the progression of TNBC by regulating the m6A methylation modification of TNFSF9 mRNA and inducing M2 polarization of TNBC tumor-associated macrophages." (PMID 40830812, 2025). "The results clarified that, compared to PTX-sensitive patients, the expression levels of RBM15 and TNFSF9 were abnormally high in the tumor tissues of PTX-resistant patients, and there was a relatively significant positive correlation between the two." (PMID 40830812, 2025). "This lactylation not only prevents RBM15 protein degradation but also enhances its interaction with the m6A methyltransferase METTL3, thereby elevating global m6A levels and further driving tumor cell proliferation and migration." (PMID 41403702, 2025). "Degraded RBM15 enhances the stability of TPM1 mRNA in an m6A-dependent manner, contributing to tumor resistance acquisition." (PMID 38798700, 2024). "Our results align with these findings, as we observed that RBM15 is highly expressed in NSCLC and positively correlates with tumor size (> 3 cm) and advanced TNM stage (III and IV)." (PMID 39716068, 2024). "We found that AZGP1P2 was downregulated in PCa and stem-like tumor cell Mechanistically, AZGP1P2 combines with RBM15 and ubiquitin-like modifier activating enzyme 1, promoting the ubiquitination and degradation of the former at the protein level." (PMID 38798700, 2024). "Collectively, these results imply that AZGP1P2 mediates the stemness and apoptosis of PCSCs and promotes docetaxel therapeutic effect by suppressing tumor growth and metastasis via UBA1/RBM15-mediated TPM1 mRNA decay in CRPC." (PMID 37854295, 2023). "Immunohistochemical images showed the expression levels of RBM15, VIRMA, YTHDC2, YTHDF2, METTL14, and IGF2BP2 proteins in tumor tissues." (PMID 36791151, 2023). "Particularly, m6A writers showed high up-regulated expression in tumor samples, such as METTL3, RBM15, RBM15B and WTAP." (PMID 35847857, 2022). "Yellow background indicated the most significant (p < 0.0001) genes up-regulated in tumor tissues, including HNRNPC, YTHDF1, IGF2BP1, YTHDF2, RBM15, and IGF2BP3." (PMID 35581263, 2022).
tumor (continued). "In this study, we found that the expression of m6A regulators was up-regulated in HCC tissues, and the up-regulated expression of YTHDF1/2, YTHDC1, RBM15 and METTL3 was significantly correlated with the tumour stage of HCC patients." (PMID 36434140, 2022). "We found that with the exception of RBM15/15B, YTHDF2, ZC3H13, all other regulators were significantly correlated with tumor occurrence (P < 0.05)." (PMID 35572524, 2022). "Subsequently, we explored the difference in expression between tumor tissues and adjacent tissues of PAAD and observed that WTAP was notably downregulated in tumor tissues, whereas RBM15, IGFBP1/3, and YTHDF1 seemed upregulated in tumor samples." (PMID 35606813, 2022). "The results revealed that tumor tissues had significantly higher expression of DDB2, MSI2, and RBM15 than the normal tissues." (PMID 35288483, 2022). "To validate the oncogenic role of YES1 in HCC, we compared the mRNA levels of YES1 between tumor and normal tissues and analyzed the co-expression between YES1 and RBM15." (PMID 34707107, 2021). "RBM15 was mainly located in the nucleus in LSCC tissues, and the expression level in cancer tissues was significantly higher than that in adjacent non-tumor tissues." (PMID 33637103, 2021). "The results showed that ELAVL1, YTHDF2, RBM15, HNRNPA2B1, ALKBH5A, and RBM15B expression was significantly upregulated in tumor tissues compared with normal tissues (p < 0.05)." (PMID 34900988, 2021). "It appeared that IGF2BP1/3, ELAVL1, HNRNPA2B1, HNRNPC, KIAA1429, RBM15, LRPPRC, FMR1, YTHDF1/2 are highly expressed in the tumor while FTO, METTL14/16, WTAP, YTHDC1 and ZC3H13 are down-regulated." (PMID 35095993, 2021). "Specifically, YTHDF1, IGF2BP2, KIAA1429, RBM15, IGF2BP1, ZC3H13, and METTL3 were significantly up-regulated in tumor tissues by unpaired T-tests (P < 0.05), while ALKBH5, YTHDC2, and METTL14 were significantly down-regulated (P < 0.01)." (PMID 34149792, 2021). "Here, we observed that KIAA1429 and RBM15 had prevalent CNV alterations and significant up-regulation in tumor tissues, suggesting the potential role of promoting the migration and invasion of cancer cells." (PMID 33500720, 2021). "Especially, FTO (in all of nine tumor types), RBM15 (in seven of nine tumor types), and YTHDF1 (in six of nine tumor types) showed a wide range of inter-group expression differences." (PMID 33585244, 2020). "We examined the expression of 17 m6A-related genes in GEO database, and found that WTAP, RBM15, YTHDF1, and YTHDF2 were differently expressed in tumor tissue compared with control tissue." (PMID 32814762, 2020). "Specifically, HNRNPC, YTHDF1, YTHDF2, METTL3, RBM15, YTHDF3, and KIAA1429 are highly expressed in tumor tissues." (PMID 32258108, 2020). "Particularly, in contrast to their low CNV frequencies (< 5%) in normal samples, CBLL1, METTL14, RBM15, IGF2BP1, YTHDC1, and YTHDF2 exhibited more than 20% difference in their frequencies of CNVs between tumor and normal samples." (PMID 33585234, 2020). "Five m6A-related genes (ZC3H13, METTL14, YTHDF2, YTHDF3 and HNRNPA2B1) showed significantly downregulated in tumor tissue, while seven regulators (YTHDC2, FTO, WTAP, METTL3, ALKBH5, RBM15 and KIAA1429) was remarkably upregulated in ccRCC." (PMID 32419773, 2020). "In short, RBM15‐mediated m6A modification enhanced SRSF1 stability, and SRSF1 promoted ATP7B alternative splicing to inhibit cuproptosis, thereby promoting NSCLC cell proliferation and tumor growth." (PMID 40923717, 2026). "In LUAD, RBM15 enhances the stability of LDHA mRNA, further supporting tumor progression." (PMID 41256854, 2025). "In addition to RBM15, several other m6A methyltransferases, including METTL3, METTL14, and WTAP, play critical roles in tumor immunity by modulating RNA methylation and downstream immune responses." (PMID 41403702, 2025).
tumor (continued). "RBM15 targeted the N6-adenylate methylation (m6A) modification of TNFSF9, and overexpression of TNFSF9 could reverse the tumor-suppressing effect of silencing RBM15 on PTX-resistant TNBC cells in vitro and transplanted tumors in vivo." (PMID 40830812, 2025). "Mechanistically, RBM15 regulates downstream target ATP citrate lyase (ACLY) expression via m6A modification, which is recognized by IGF2BP2, thereby activating ACLY, driving lipid biosynthesis, and enhancing tumor malignancy." (PMID 41403702, 2025). "Additionally, WB analysis demonstrated that when RBM15 was silenced in MDA-MB-231/PTX cells, the protein level of RBM15 was down-regulated in mouse tumor tissues, accompanied by a concomitant decrease in TNFSF9 levels." (PMID 40830812, 2025). "Furthermore, the positive correlation between RBM15 and TNFSF9 in the tumor tissues of PTX-resistant patients was also proved by Spearman’s correlation analysis." (PMID 40830812, 2025). "Analysis of tumor tissues showed significant downregulation of RBM15, KLF1, and ANXA8, along with reduced m6A content (p < 0.01), while TRIM13 expression was increased (p < 0.01) in the sh-RBM15 group compared to the sh-NC group." (PMID 39716068, 2024). "Interestingly, genes with oncogenic potential, including CDC42, CDC14B, STK40, BRD3, CPNE1, and MCM3, were downregulated, whereas tumor inhibitors, including CDKN2C, CASP7, and CDKN1B, were upregulated by RBM15 depletion." (PMID 38825643, 2024). "Thus, RBM15 plays important roles in TNBC proliferation, migration, and invasion in vitro and in tumor growth in vivo." (PMID 38825643, 2024). "Importantly, RBM15 knockdown inhibited the growth of MDA-MB-231 xenografts, as evidenced by reduced tumor volume and weight." (PMID 38825643, 2024). "Thus, we first examined the expression levels of METTL3, METTL14, WTAP, RBM15, FTO, and ALKBH5 transcripts in tumor samples and corresponding normal samples using the GEPIA database." (PMID 38665783, 2024). "In this study, we examined the role of RBM15 in BC cells and found that it specifically targets SSP genes to induce m6A modification and the expression of SSP and subsequent de novo serine and glycine biosynthesis and tumor progression." (PMID 38825643, 2024). "The influence of RBM15 may be mediated via the EP300/CBP‐RBM15‐CXCL11 axis, highlighting its potential role in tumour biology." (PMID 39580709, 2024). "The findings indicated a significant increase in RBM15 expression in tumor tissues compared to non-tumor tissues." (PMID 37474926, 2023). "These outcomes suggest that the tumor suppressor effect of ANXA10 is related to m6A; ANXA10 may regulate HNRNPA2B1, IGF2BP3, METTL3, RBM15, YTHDF1 and YTHDF2 to affect the methylation level of LIHC." (PMID 36709331, 2023). "T3 + T4 tumours, III + IV tumours, and N1 tumours had higher expression levels of RBM15." (PMID 33637103, 2021). "Furthermore, combined RBM15 and SRSF1 knockdown further inhibited tumor growth." (PMID 40923717, 2026). "However, after silencing RBM15 and then overexpressing TNFSF9, the protein level of TNFSF9 in tumor tissues showed a significant rebound trend, confirming that RBM15 could also targeted and regulated TNFSF9 in vivo." (PMID 40830812, 2025). "Notably, Rbm15 knockout significantly prohibited tumorigenesis in immunocompetent mice, as evidenced by reductions in both tumor volume and weight, with no changes detected in body weights." (PMID 40370450, 2025). "Moreover, RBM15 expression was not correlated with tumor purity in LIHC or PAAD, but was negatively correlated with that in STAD." (PMID 40370450, 2025). "In addition, Rbm15 knockout significantly exhibited enhanced FH expression in MC38-derived xenograft tumors, demonstrating that RBM15 may regulate anti-tumor immune responses via FH modulation." (PMID 40370450, 2025).
tumor (continued). "A recent study has further proposed that the knockdown of RBM15 effectively reduces the levels of TGF-β and Smad2, and promotes ferroptosis by regulating genes related to the iron concentration process, thus inhibiting proliferation, migration, invasion, and tumor growth." (PMID 38915367, 2024). "Importantly, we found that RBM15 expression was associated with patient survival in basal-like BC/TNBC patients, indicating that the prognostic effects of RBM15 are not solely driven by tumor subtype." (PMID 38825643, 2024). "In addition, RBM15 expression was significantly greater in basal-like BC/TNBC cell lines than in non-basal-like tumor BC/non-TNBC cell lines." (PMID 38825643, 2024). "Furthermore, we found that the high RBM15 expression score is not significantly related to the patient’s age of onset, family history, tumor diameter size, neutrophil count, liver and kidney function, and other indicators." (PMID 36831430, 2023). "Furthermore, UALCAN revealed that the gene expression differences in METTL3, RBM15, RBM15B, VIRMA and CBLL1 may also be related to tumor grade." (PMID 35223847, 2022). "Moreover, five pairs of clinical specimens were collected to confirm the overexpression of HNRNPC and non-ectopic expression of RBM15 in tumor tissues." (PMID 33952721, 2021). "Similarly, overexpression of HNRNPC was detected in clinical tumor tissues by qPCR but not for RBM15." (PMID 33952721, 2021). "Most increased regulators in tumor cases compared to normal cases were YTHDF2 (p < 0.001), FTO (p < 0.001), YTHDC1 (p < 0.001), YTHDC2 (p < 0.001), YTHDF1 (p < 0.001), KIAA1429 (p < 0.001), METTL3 (p < 0.010), WTAP (p < 0.001), RBM15 (p < 0.001), HNRNPC (p < 0.001), and ALKBH5 (p = 0.001)." (PMID 32733931, 2020). "However, the role of RBM15 in tumor immunity has not been elucidated." (PMID 35223996, 2022). "However, there was no expressive difference of RBM15 between tumor and normal samples." (PMID 33952721, 2021). "Differential expression analysis indicated that the protein expression levels of KIAA1429, RBM15, HNRNPC, HNRNPA2B1, YTHDF1, YTHDF2, and YTHDC1 were higher in tumor samples than in non-tumor samples." (PMID 32582536, 2020). "The compared with adjacent non-tumorous tissues, we found a higher level of RBM15, IGFBP1, RBMX, FTO, and ALKBH5 in all five STAD tissues, RBM15, FTO and ALKBH5 were overexpressed in STAD tumor tissues, while the expression of IGFBP1, RBMX was not changed in STAD tumor tissues." (PMID 37019148, 2023).